RNU6-774P (RNA, U6 small nuclear 774, pseudogene)
Gene: Small nuclear RNA gene on chromosome 4 (84,233,657 to 84,233,763, forward strand). Ensembl gene ENSG00000200108.
Homologues: Orthologues: chimpanzee U6 (97% identical), macaque U6 (97% identical), dog U6 (89% identical), rabbit U6 (84% identical), pig U6 (82% identical). Paralogues in human: RNU6-86P (93% identical), RNU6-28P (93% identical), RNU6-11P (92% identical), RNU6-1309P (92% identical), RNU6-37P (92% identical), RNU6-38P (92% identical), RNU6-560P (92% identical), RNU6-890P (92% identical), RNU6-21P (91% identical), RNU6-235P (91% identical), RNU6-33P (91% identical), RNU6-468P (91% identical), and 1283 more.